BRCA1 (BRCA1 DNA repair associated)
Diseases named in the same sentence as BRCA1 in open-access papers (continued):
Sharing a sentence is not in itself a finding about the gene and the disease.
breast cancer (continued). "However, pathogenic changes in BRCA1/2 do not account for all cases of hereditary breast cancer, and additional genes are associated with an increased cancer risk." (PMID 31890060, 2019). "Despite the small sample size, the prospective nature of the analysis along with the ability to adjust for potential confounders suggests that RANKL is likely not a circulating biomarker of breast cancer risk among women with an inherited BRCA1 or BRCA2 mutation." (PMID 31069010, 2019). "Since loss of BRCA1 leads to the hyperactivation of mTORC2, it may be possible that breast cancer cells lacking BRCA1 could be dependent upon mTORC2 signaling and more sensitive to its inhibition." (PMID 31771139, 2019). "Mutations in the BRCA1 and BRCA2 genes represent a predisposing factor for breast cancer, similarly to a family history of breast cancer or personal history of neoplastic diseases or breast cancer Finally, dense breast is an independent risk factor of breast cancer." (PMID 30934972, 2019). "Therefore, we hypothesized that the difference in immunophenotype between BRCA1- and BRCA2-deficient breast cancers may be attributed to PTEN loss, such as that mediated by inactivating PTEN gene mutations." (PMID 31022191, 2019). "The clinical characteristics of breast cancer in patients with the BRCA1 L63X mutation might not differ from those caused by other BRCA1 or BRCA2 mutations, except the subtype and nuclear grade of the resultant cancer." (PMID 31143373, 2019). "Although many in vitro studies have demonstrated an overproduction of ROS and increased free radical damage caused by the BRCA1 mutation, the mechanisms responsible for the induction of oxidative stress in patients with breast cancer have not been explained in detail." (PMID 31597313, 2019). "Although not directly related to breast cancer, some evidences have been suggesting that hypomethylation of BRCA1 might be associated with an increased carcinogenic risk." (PMID 31261650, 2019). "Recently, three studies which were conducted in the United States, Russia, and China used gene panel sequencing to screen the multi-gene germline mutations in high-risk BRCA1/2-negative breast cancer patients, yet none of the FANCC germline mutations were found." (PMID 30967997, 2019). "In our study, it indicated an overall 18.4% (17.6% before age 50 years) prevalence of deleterious BRCA1/BRCA2 mutations in high‐risk women diagnosed with DCIS, supporting the presence of an in situ phase of carcinogenesis in the development of at least some BRCA‐associated breast cancer." (PMID 30652428, 2019). "After MYC amplification, the next most common alterations in our analysis of the human BRCA1-deficient TNBCs were mutations and/or amplifications of PIK3CA (23/80 cases), indicating that activation of PI3K signaling is an important driver in this breast cancer subtype." (PMID 30674894, 2019). "CN analysis revealed that the 17 BRCA1-associated breast cancers with bi-allelic inactivation had higher frequencies of gains of 3q and 6p and losses of 17q, among other differences (P < 0.05, Fisher’s exact test), as compared to the 16 PALB2-associated breast cancers with bi-allelic inactivation." (PMID 31428676, 2019). "In this study, we describe the molecular characterization of CD10+ myoepithelial cell population from normal breast tissue of healthy control nulliparous and parous women with no family history of breast cancer, and BRCA1/2 mutation carriers, as well as from DCIS." (PMID 31519911, 2019). "Similarly, the G allele of rs2910164, located within miR146a which may bind to the 3′ untranslated regions of the BRCA1 and BRCA2 genes and thus regulate their expression, has been associated with breast cancer risk (OR=1.77; 95% CI=1.40-2.23)." (PMID 31379942, 2019).
breast cancer (continued). "We found no changes in the concentrations of oxidative modification products in breast cancer patients without the BRCA1 mutation, which corroborates our earlier observations regarding the relationship between cancer, the BRCA1 mutation, and disorders of redox balance." (PMID 31597313, 2019). "The level of pPh tended to be lower in women with breast cancer and without the BRCA1 mutation." (PMID 31597313, 2019). "While the role of the BRCA1 gene (MIM *113705) in breast cancer (BC) and ovarian cancer (OC) predisposition is well established, the role of BARD1 (MIM *601593) in BC/OC predisposition remains elusive." (PMID 31036035, 2019). "Of note, 60–90% of germline mutation BRCA1-associated breast cancers are HR negative, which may be a possible explanation for the increased second SPCs in HR-negative IPBC patients." (PMID 31998630, 2019). "Subsequent studies have led to the suggestion that the preinvasive phase may be shortened or even absent in hereditary breast cancers, particularly those associated with BRCA1 mutations (Jacquemler, Eisinger, Guinebretiere, Stoppa‐Lyonnet, & Sobol, 1996)." (PMID 30652428, 2019). "A total of 325 Japanese women with breast cancer (BC) (with or without invasive cancer) were referred for genetic counseling and underwent genetic testing for mutations in the BRCA1 and BRCA2 genes in Showa University Hospital between December 2011 and August 2016." (PMID 30652428, 2019). "Moreover, in HPV-positive breast cancer patients BRCA1 and BRCA2 were decreased (both P < 0.001) compared to the HPV-negative group., suggesting that the role of HPV in breast cancers could be accomplished through interacting with these proteins." (PMID 30642295, 2019). "Compared with normal mammary tissues, cyclin D1 was overexpressed in asynchronous cultured cells from Brca1-mutant tumors, but cyclins A, B1, and E were not detectable, indicating that mammary tumors caused by the loss of BRCA1 are associated with a deficiency of cyclin B116." (PMID 30327455, 2018). "Nevertheless, an evaluation for carriers of BRCA1 mutations in Hispanic, AA, and Asian American breast cancer patients compared with non-Hispanic white patients, with and without Ashkenazi Jewish ancestry, indicated a prevalence of pathogenic BRCA1 mutations in minority racial populations." (PMID 29690565, 2018). "Furthermore, deletion of mouse Palb2, another breast cancer susceptibility gene with functional similarities to BRCA1, does not rescue Cobra1 knockout-associated mammary defects." (PMID 29426838, 2018). "Our study demonstrates that about nine percent of medullary like breast cancer patients without any known positive family history were BRCA1 gene mutation carriers, whereas no pathogenic somatic BRCA1/2 mutations could be found." (PMID 29453630, 2018). "Others have been recently approved for the treatment of specific breast cancer subtypes, such as the mTOR inhibitor everolimus in advanced luminal breast cancer and the poly(ADP-ribose)polymerase (PARP) inhibitor olaparib in metastatic breast cancer with germline BRCA1 or BRCA2 mutations." (PMID 30038706, 2018). "Given that BRCA1 and BRCA2 were identified more than 20 years ago, preventive mastectomy remains the gold standard, and mutation carriers have strong preferences for chemoprevention, it is timely that an effective breast cancer risk reduction option be identified." (PMID 30572612, 2018). "BRCA1-deficient breast tumours often present as difficult to treat triple negative breast cancers (TNBC) not dissimilar to the basal-like molecular subtype of breast cancer, which lack expression of hormone receptors and easy to target growth signals." (PMID 30323900, 2018). "BRCA1 R1699Q, a point mutation found in non-familial breast cancer patients, results in the failure of BRCA1 to recruit HDAC2 to the miR-155 promoter leading to histone acetylation and a subsequent increase in miR-155 expression contributing to breast tumourigenesis." (PMID 30323900, 2018).
breast cancer (continued). "However, mutations to BRCA1 is not supposed to be the most important causal mutation only due to the relatively low mutation recurrence in breast cancers, which was at 6 out of 516 patients." (PMID 29485617, 2018). "Interestingly, a rare germline BRCA1 mutation was found in one male MA patient without a personal or family history of breast cancer, prostatic cancer, or pancreatic cancer." (PMID 30111351, 2018). "For example, the word “genes” occurring throughout the tool might have highlighted the important message that BRCA1/2 means breast cancer genes, thus leading to more correct responses for Q1 from the NGCT group compared to those where information was communicated through words alone." (PMID 30001421, 2018). "Given that carriers of germline BRCA1 or BRCA2 alterations are more likely to develop breast cancer, it is arguable that mastectomy may be indicated instead of breast-conserving surgery in all carriers to prevent local recurrence in the remaining breast tissue." (PMID 30174725, 2018). "Women with germline BRCA1 or BRCA2 mutations are recommended to undergo salpingo-oophorectomy bilateral (prophylactic oophorectomy, RRSO) to reduce their risk of developing ovarian cancer (and breast cancer), usually by age 40 or after the completion of child bearing." (PMID 29389895, 2018). "Our study might add information to consider prevention strategy of early-onset and high-risk breast cancers in Asia, and also to the genetic counseling for relatives of the high-risk breast cancer patients without a mutation in BRCA1/2 genes." (PMID 30323354, 2018). "The increased risk of developing breast cancer has been linked to atypical hyperplasia which often exhibits loss of PRB, equally, altered ER expression, sole PRA expression, and preferential PRB loss is also reported in the normal breast tissue of women with germline BRCA1/2 mutations." (PMID 29600163, 2018). "We evaluated the incidence and spectrum of pathogenic and likely pathogenic variants of cancer susceptibility genes in BRCA1/2 mutation-negative Korean patients with a high risk for hereditary breast cancer using a comprehensive multigene panel that included 35 cancer susceptibility genes." (PMID 29338689, 2018). "First, for Nigerian women, BRCA1 and BRCA2 have a major effect on breast cancer incidence both because the ORs for BRCA1 and BRCA2 are extremely high (> 20 for BRCA1; > 10 for BRCA2) and because 11% of patients carry a damaging mutation in one of these genes (7.0% in BRCA1; 4.1% in BRCA2)." (PMID 30130155, 2018). "On Dec 5, 2016, we did another PubMed search for studies of patients who carried a BRCA1 or BRCA2 mutation and their prognosis, using the following search terms: “(BRCA) AND (survival or prognosis or outcome or mortality) AND (breast neoplasms or breast neoplasm or breast cancer or breast tumour)”." (PMID 29337092, 2018). "In contrast, not all “triple negative” breast cancer patients have a germline BRCA1/2 mutation." (PMID 29453630, 2018). "BRCA1/2 mutations are not uncommon among selected Jordanian females with breast cancer." (PMID 29409476, 2018). "Finally, we analyze public expression data and find that other TSGs, including LATS1 and BRCA1, also undergo intronic pPA following large internal exons, and that m6A levels in these exons are reduced in pPA-activated breast cancer cells relative to untransformed mammary cells." (PMID 29362392, 2018). "However, these fibroblasts from benign hyperplasia could respond to cm from BRCA1 defective breast cancer cells with high induction of CCL5." (PMID 30224826, 2018). "Moreover, since many of the recruited high risk patients tested negative for BRCA1/2 mutations, it is plausible to take advantage of the collected DNA samples and test for mutations in other breast cancer susceptibility genes, e.g. CHEK2, PALB2 and BRIP1." (PMID 29409476, 2018).
breast cancer (continued). "In addition, a case-control study by the Hereditary Ovarian Cancer Clinical Study Group found that tubal ligation lowered the rate of OvCa among BRCA1 carriers by 60%, after adjustment for oral contraception use, parity, history of breast cancer, and ethnic group." (PMID 30363743, 2018). "On the other side, RAD54B is a telomere-related gene involved in DNA repair process, and coding-missense changes of this gene have been found in familial breast cancer cases not explained by mutations in the best-known high susceptibility genes BRCA1 and BRCA2." (PMID 30211214, 2018). "The ESMO clinical practice guidelines for primary breast cancer published in 2015 do not recommend platinum agents for routine use for BRCA1/2 mutation carriers; however, these guidelines state that adding a platinum compound to NACT, after discussion with the patient, is acceptable." (PMID 29719582, 2018). "Previous studies and meta-analyses have reported inconsistent effects of BRCA1 and BRCA2 mutations on the outcomes of early breast cancer with better, worse, and similar outcomes for patients with a BRCA1 or BRCA2 mutation compared with patients with sporadic breast cancer." (PMID 29337092, 2018). "Within Asia, a South Korean study of 235 patients at high-risk for hereditary breast cancer and were confirmed not to have a BRCA1/2 mutation were tested with massively parallel sequencing, and 3.6% were found to have pathogenic germline mutations in CHEK2, PALB2, MRE11 and RAD50." (PMID 30093976, 2018). "By this approach, we identified loss‐of‐function mutations in 6/20 (30%) probands, five of which occurred on BRCA1, CHEK2, and ATM and are esteemed to be risk‐relevant according to our studies, while a novel RAD50 truncating mutation is most likely unrelated to breast cancer." (PMID 29271107, 2018). "Furthermore, decreased BRCA1 expression, due to promoter hypermethylation or somatic mutations, have been reported in sporadic breast cancers, regardless of breast tumor subtypes." (PMID 28646826, 2018). "Here we observe that EDC4, besides its known role in processing-bodies (P-bodies), interacts with BRCA1 and is involved in HR-mediated DNA repair by regulating its end-resection step and that germline mutations in EDC4 may confer increased risk of breast cancer." (PMID 29511213, 2018). "Furthermore, we revealed that SIRT1 deficiency is associated with substantial induction of acetylated markers on six breast cancer-related gene promoters: AR, BRCA1, ERS1, ERS2, EZH2, and EP300, suggesting an active role of SIRT1 in regulating the expression of these genes in BC." (PMID 30380732, 2018). "Thus, genetic ablation of Cobra1 ameliorates Brca1-associated R-loop accumulation and mammary tumour development, but it does not appear to affect progression of Brca1-associated tumours once they are formed." (PMID 28649985, 2017). "Through the literature reports, along with our data, we can infer that a significant portion of patients at risk for hereditary breast cancer (mutated or not in BRCA1) show a reduction in gene expression levels of BRCA1, requiring more studies to elucidate these findings." (PMID 27926510, 2017). "Indeed, cells overexpressing IRIS show many of the properties of TNBC cells, including high expression of the basal-biomarkers, EMT-inducers, and stemness-enforcers, as well as low expression of the BRCA1 protein, in culture, orthotopic mammary tumors, as well as human tumor samples." (PMID 29262555, 2017).
breast cancer (continued). "Whether VDR, RXR or PPARγ are expressed in BRCA1 mutated breast cancer or may even be present in case of triple negativity is not known." (PMID 28427429, 2017). "Personal history of breast cancer, with and without a family history of ovarian cancer, was the primary criteria used to select individuals for this study from among all those who had previously tested negative for BRCA1 and BRCA2 mutations." (PMID 28281021, 2017). "Moreover, breast cancer patients with inherited BRCA1 variants have a higher frequency of copy number alterations than those without inherited BRCA1 variants." (PMID 27821817, 2017). "In addition, eight selected variants were genotyped using TaqMan assays in 807 BRCA1/2-mutation negative breast cancer patients and 1690 healthy women." (PMID 28279176, 2017). "Besides, also found that loss of PTEN protein expression was significantly associated with the basal-like cancer subtype in both nonhereditary breast cancer and hereditary BRCA1-deficient breast cancer." (PMID 29322925, 2017). "Therefore, we next determined whether the down-regulation of CTSO inhibited cell proliferation in breast cancer cells due to the up-regulation of BRCA1." (PMID 28968398, 2017). "Recent data suggest approximately 10% of young or familial TNBC patients with no BRCA1 or BRCA2 mutation carry inherited deleterious mutations in other breast cancer predisposition genes, particularly in genes involved in HRR such as PALB2, BARD1, RAD51C, RAD51D, and BRIP1." (PMID 29108297, 2017). "Furthermore, BRCA1 mutation carriers had increased breast cancer mortality if they did not receive chemotherapy." (PMID 29152070, 2017). "In addition, consanguinity should protect against breast cancer caused by BRCA1 and BRCA2 which is not a case in this population." (PMID 29157216, 2017). "However, they found a correlation between survival rate in breast cancer and expression of BRCA1." (PMID 29021870, 2017). "The protein level of BRCA1 has been often found to be low in sporadic breast cancer patients with no family history of the disease or BRCA1 mutation, suggesting the existence of other factors or mechanisms that control the BRCA1 protein levels during mammary tumorigenesis." (PMID 29156836, 2017). "The MLPA test for BRCA1 mutation could be recommended for breast cancer patients with a family member with breast and/or ovarian cancer and additional personal factors, and who tested negative for BRCA1/2 small mutations in initial testing." (PMID 28205045, 2017). "Importantly, we found a positive correlation between Rak and BRCA1 expression in breast cancer despite not knowing information about the mutation status of Rak and BRCA1." (PMID 29156836, 2017). "Most non-BRCA1/2 breast cancer families have no identified genetic cause." (PMID 29262523, 2017). "Degradation of BRCA1 is also mediated by the proteasome after HERC2 (HECT-type E3 ligase) targeting; BRCA1, together with its partner BARD1 (BRCA1-associated RING domain 1), have an important role in HR and loss of any of these proteins results in susceptibility to breast cancer." (PMID 28937603, 2017). "Patients carrying a BRCA1 germline mutation overexpressed VDR (BRCA1mut vs. sporadic: IRS 6.00 vs. IRS 3.00%, p < 0.001), RXR (BRCA1mut vs. sporadic: IRS 6.00 vs. IRS 3.00, p = 0.010) and PPARγ (BRCA1mut vs. sporadic: IRS 2.00 vs. IRS 0.00, p < 0.001) when compared to sporadic breast cancer." (PMID 28427429, 2017). "Several FA genes (FANCD1/BRCA2, FANCN/PALB2, FANCJ/BRIP1, FANCO/RAD51C, and FANCS/BRCA1) are high- or moderate-risk breast or ovarian cancer susceptibility genes and previous studies have connected also heterozygous FANCM mutations with breast cancer predisposition." (PMID 28702895, 2017).